POSTN (periostin)
Diseases named in the same sentence as POSTN in open-access papers (continued):
Sharing a sentence is not in itself a finding about the gene and the disease.
tumor (continued). "Although the stroma of cancer tissues is the main source of POSTN, it is still unclear how POSTN facilitates the interplay between cancer cells and CAFs in NSCLC, thereby promoting tumour initiation and progression by modifying the tumour microenvironment." (PMID 32987711, 2020). "Finally, thrombospondin 2 (TSP2) secreted by endothelial cells maintains solitary DTCs in a dormant state, while TGFβ1 and periostin (POSTN) promote dormancy exit, leading to an increase in tumor size and recurrence." (PMID 32260071, 2020). "We have previously shown that GSCs secrete Periostin to recruit monocyte-derived TAMs into GBMs18, but how TAMs are educated and maintained as M2 tumor-supportive macrophages in the tumor microenvironment in GBM has not been defined." (PMID 32541784, 2020). "Hence, the overall data suggest a complex paracrine regulation of the Wnt pathway in cancer cells by TGF-beta-activated CAFs through POSTN secretion and YAP activation in order to enhance tumor progression and metastasis formation." (PMID 33553157, 2020). "Periostin also interacts with various cell-surface receptors, particularly with integrins, through the PI3K/AKT signaling pathway to promote epithelial-mesenchymal transition (EMT), cell growth, and tumor angiogenesis and invasion." (PMID 32719746, 2020). "Periostin, a cell-adhesion ECM protein, is increased in physiological processes involved in skin repair, fibrosis, cell proliferation, and ECM remodeling, and tumor processes such as growth and metastasis." (PMID 31440236, 2019). "Many components of this family such as periostin (POSTN), osteopontin (SPP1), or the CNN family of proteins have been shown to regulate key aspect of tumor biology, including proliferation, invasion, matrix remodeling, and dissemination to pre-metastatic niches in distant organs." (PMID 29946533, 2018). "We noted that periostin was frequently expressed in the smooth muscle wall of small blood vessels within non-lesional bone around growing tumours, both benign and malignant." (PMID 30202513, 2018). "The functional role of MAM-derived periostin in PDAC metastasis and the tumor-secreted factors that regulate MDSC activity remain speculative." (PMID 29903049, 2018). "Periostin expression in the stroma ranged from weak to strong, but was consistently absent in the tumor area in all specimens." (PMID 30131847, 2018). "Periostin is also known to modify the ECM and could then increase proliferation via modifying other ECM-mediated signaling from the tumor microenvironment." (PMID 29507310, 2018). "A similar analysis of GBM4 xenografts was practically limited by the invariable growth and small tumor sizes of TW‐deficient GBM4 tumors, yet these cells demonstrated TW‐dependent regulation of POSTN and AKT without in vivo selection." (PMID 29754406, 2018). "Together, these data show that periostin is specifically required for proliferation and invasion, but not for anti-apoptosis function of mesenchymal tumor cells in response to chemotherapy." (PMID 29507310, 2018). "Inducing neo-angiogenesis could be a key milestone for tumours escaping dormancy, as endothelial tip cells are a source of tumour-promoting transforming growth factor β1 (TGF-β1) and periostin that seem to overcome the effects of thrombospondin." (PMID 28098771, 2017). "In summary, we found that expression of POSTN in cancer stromal cells, rather than in tumor cells, not only serves as a prognostic factor for clinical outcome but also an important indicator for platinum response in EOC patients." (PMID 26716408, 2016). "While numerous markers, such as PDGFRα, periostin and fibroblast activation protein (FAP) have been reported to identify CAF within the tumor microenvironment, SMA is most commonly used to identify those CAF with an ‘activated’ tumor-promoting myofibroblastic phenotype." (PMID 27992856, 2016).
tumor (continued). "Additionally, signal molecules produced by tumor cells, such as lactate, HRG/PIGF, chemokine ligand 2 (CCL2), soluble colony-stimulating factor 1 (sCSF1), and POSTN, play critical roles in macrophage polarization." (PMID 27683110, 2016). "A 5-gene PDAC classifier (TMPRSS4, AHNAK2, POSTN, ECT2, SERPINB5) achieved on average 95% sensitivity and 89% specificity in discriminating PDAC from non-tumor samples in four training sets and similar performance (sensitivity = 94%, specificity = 89.6%) in five independent validation datasets." (PMID 26993610, 2016). "POSTN, PPEF1, SAMSN1 and TNFSF13B were upregulated in a great majority of the ccRCC tumours." (PMID 27358011, 2016). "Upregulation of genes such as POSTN, TNFSF13B and SAMSN1 could provide increased metastatic potential of the tumour, as discussed." (PMID 27358011, 2016). "Here, we showed that higher POSTN expression in cancer stromal cells, rather than in tumor cells, was significantly correlated with shorter disease-specific progression-free survival (PFS) and overall survival (OS) in multivariate analysis." (PMID 26716408, 2016). "Further study demonstrated that patients with periostin-positive in tumor had worse prognosis than those periostin-negative patients in OS (46.80 vs. 76.45 months) and DFS (47.45 vs. 80.67 months), respectively." (PMID 26822225, 2016). "Although TGF-β3 is likely to propel the metastasis of tumor cells to some extent, it is undisputed that TGF-β3 could induce POSTN expression during the co-culture." (PMID 26857387, 2016). "Taken together, these findings suggest that POSTN promotes tumor angiogenesis via Erk/VEGF signaling in PaC and POSTN may be a new target for cancer anti-vascular treatment." (PMID 27223086, 2016). "Studies showed that periostin did not have a direct effect on the growth of tumor cells, however, knocking out periostin leads to a significant reduction in the metastatic potential." (PMID 27092178, 2016). "Secondary tumours, those that metastasize to new locations, are incapable of surviving without the presence of Periostin." (PMID 26543579, 2015). "NOF-conditioned medium supplemented with recombinant POSTN or CAF-conditioned medium promoted EAC invasion (>3.5-fold) and this was inhibited by the addition of αvβ3- or αvβ5-blocking antibodies, or a PI3K inhibitor, LY294002, to the tumour cells." (PMID 25345775, 2015). "High stromal periostin expression was observed in the mouse xenograft model containing OE33 and CAFs, and activation of Akt was confirmed in this model by high pAkt staining in adjacent tumour cells." (PMID 25345775, 2015). "Periostin, tenascin and osteopontin are the main non-structural secreted matricellular proteins which form a key component of both desmoplastic tumor stroma and granulation tissue." (PMID 26421614, 2015). "Patients with no periostin staining in their resected tumours had a mean time to recurrence of 80.67 months (median not yet reached)." (PMID 25345775, 2015). "Periostin is a driver of the epithelial–mesenchymal transition (EMT) and induces expression of MMP-9, MMP-10, and MMP-13, resulting in the degradation of ECM, believed to be crucial for local tumor spread and/or metastasis." (PMID 24146092, 2014). "Periostin mRNA has been shown to be upregulated in NSCLC tissue in relation to normal lung tissue, and also to be correlated with adeno cell subtype and higher tumor grade." (PMID 24273600, 2013). "POSTN, the most overexpressed gene in the T/N comparison, stained stroma (all 4 cases) around the tumor cells but not near normal cells." (PMID 22280838, 2012). "Importantly, serum level of periostin and VEGF-C was well correlated with tumor progression including lymph node metastasis." (PMID 22952986, 2012). "We used these tumor tissues (10 control and 10 periostin-overexpressing tumors) to count the numbers of lymphatic vessels expressing LYVE-1, which was specifically observed in lymph vessels in both control and periostin-overexpressing tumors." (PMID 22952986, 2012).
tumor (continued). "Importantly, the serum periostin level in HNSCC patients correlated well with that of VEGF-C and with malignant behaviors including increased tumor stage and lymph node metastasis." (PMID 22952986, 2012). "Periostin in particular seems to offer attractive therapeutic possibilities, as it is secreted and expressed selectively in tumor but not in normal stroma." (PMID 21611158, 2011). "The tissues of all 18 xenografts expressed strong positive Periostin in the stroma and the tissues of 12 xenografts from the groups of normal LNCap cells and control GFP-LNCap cells also expressed strong positive Periostin in the tumor cells." (PMID 21714934, 2011). "In the remaining tumour epithelia, periostin was detected in the cytoplasm without luminal or membranous accentuation." (PMID 20534149, 2010). "The mRNA expression level of six soluble factors already recognized in cancer biology (POSTN, TNC, CSPG2, LOXL1, ATRN, FBS1) increases in response to IGF-I stimulation, suggesting that these factors play some role in stimulating tumour cell proliferation and metastasis." (PMID 20051100, 2010). "To date, no quantitative comparison of periostin expression in a large panel of normal and tumor tissues was available." (PMID 18086302, 2007). "Regarding biological functions, let-7f inhibits tumor cell proliferation, invasion, metastasis, stemness maintenance, and metabolic reprogramming by targeting multiple oncogenes (e.g., MYH9, HMGA2, ADAMTS1, Periostin) and key signaling pathways (e.g., MAPK, Wnt, PI3K/AKT)." (PMID 42293764, 2026). "Bevacizumab (anti‐VEGF) normalizes tumor vasculature to enhance T cell infiltration; paired with galunisertib, it may suppress hmmyCAF TGF‐β signaling, disrupting collagen XV barriers and POSTN‐checkpoint interactions." (PMID 41057994, 2025). "POSTN can reshape the structure and composition of the ECM, alter the migration and infiltration abilities of T cells in the TME, making it difficult for T cells to reach the area where tumor cells are located, and thus unable to exert effective killing effects." (PMID 41018265, 2025). "In the 3D organoids, there were noticeable deposits of trichrome stain, Collagen 3A1 (COL3A1), periostin, as they are ECM markers that have been explored in UF, ‐catenin, since it is involved in UF pathogenesis and Oestrogen Receptors (ERα) as this isa hormonal dependent tumour." (PMID 40108998, 2025). "POSTN mRNA expression was positively correlated in tumor tissues, but not in non-tumor tissues." (PMID 41018265, 2025). "In clinically established metastases, we showed that most tumor cells were clustered around small blood vessels (ERG+, SDF1+, POSTN+, SMA+, PDGFRB+), suggesting that other cell interactions, especially involving blood vessels, might drive later stages of metastasis growth." (PMID 40841830, 2025). "Even if POSTN in the tumor cells themselves is knocked down, POSTN from non-cell-autonomous sources may still maintain residual invasive ability, which may be one of the reasons for early recurrence in some patients with low POSTN expression." (PMID 40991535, 2025). "This heterogeneity implies that simply targeting POSTN in tumor cells may not be sufficient to inhibit the CAF-driven tumor-promoting microenvironment." (PMID 41018265, 2025). "The binding of POSTN to these integrins initiates downstream signaling cascades that is a key driver of HCC progression, influencing a wide range of cellular processes, including tumor cell proliferation, metastasis, immune escape, cancer stemness and angiogenesis." (PMID 41018265, 2025). "Furthermore, the presence of both DDR2- and POSTN-expressing CAFs resulted in a greater tumor load than the presence of CAFs lacking DDR2 and POSTN." (PMID 38903506, 2024). "Therefore, chemotherapy-induced apoptosis or necrosis of tumor cells in the initial cycles may lead to a significant increase in serum CA15-3 and CEA levels, while POSTN may have already been degraded during the detection window period." (PMID 38504252, 2024).
tumor (continued). "In this study, we identified POSTN and FLNB as potential mediators of the effects of EVs on GSC and HMVEC behavior confirming that EVs play a crucial role in the intercellular communication by delivering bioactive molecules in the surrounding milieu modulating tumor microenvironment." (PMID 38347567, 2024). "In addition, periostin drives the epithelial–mesenchymal transition (EMT) via induction of matrix metalloproteinase 9 (MMP‐9), MMP‐10, and MMP‐13 expression, resulting in local tumor spread via extracellular matrix degradation." (PMID 36691359, 2023). "We document pharmacological inhibition of pro-inflammatory cytokines POSTN and CCL2 in the TME following combinatorial treatment of erlotinib+MLN0128 and propose that the effectiveness of the dual therapy is a result of both direct anti-tumor activity and modulation of the TME." (PMID 36831214, 2023). "Collectively, our findings suggest that Periostin ablation was not sufficient to abrogate the promotion of tumor growth following cardiac remodeling, due to the elevation of multiple growth factors that include pro-inflammatory and tumorigenic cytokines and Fibronectin." (PMID 38139195, 2023). "Then, several potential differentially activated pathways between tumor cells and other cells were selected, including IL17 signaling pathway, IFN-II signaling pathway, VEGF signaling pathway, PERIOSTIN signaling pathway, TWEAK signaling pathway, and PAR signaling pathway." (PMID 37122693, 2023). "The POSTN-blocking treatment did not impact primary tumor growth significantly." (PMID 37069149, 2023). "In addition, POSTN expression could serve as a predictive factor for prognosis, or a biomarker for NSCLC tumour progression." (PMID 38115703, 2023). "Moreover, POSTN mRNA expression positively correlated in tumor tissues, but not in non-tumor tissues." (PMID 35676936, 2022). "In addition to collagens, the ECM of PDAC is composed of TNC and POSTN, which we have previously identified as downstream targets of Prrx1, which fosters liver metastasis in PDAC; therefore, they can be considered key molecules in tumor progression." (PMID 35000025, 2022). "Our data indicated that POSTN acted via integrin-dependent NF-κB and TGF-β2 signaling to induce production of cytokines/chemokines from cancer cells to promote mobilization and differentiation of M2 macrophages and activate CAFs in tumor microenvironment, resulting in enhanced growth and metastasis." (PMID 36550569, 2022). "POSTN is not the only ECM protein that has the ability to regulate tumor angiogenesis." (PMID 36077762, 2022). "In addition to tumor stromal cells, tumor cells also secrete numerous ECM components, primarily collagens, fibronectin, laminins, hyaluronan, tenascin C, and periostin, which are highly expressed in metastatic tumors and contribute to building tumor metastasis niches." (PMID 35033172, 2022). "Of particular interest was periostin (POSTN), which was found to have a significantly higher expression in DDR2-expressing NOFs co-cultured with ES2 tumor cells (NOF siCTRL + ES2) compared to DDR2-depleted NOFs co-cultured with tumor cells (NOF siDDR2 + ES2) (Fold change = 2.0, p = 0.03)." (PMID 35884543, 2022). "Similar to CEA and CA153, serum POSTN was not elevated in all BCa patients, and there were obvious individual differences in serum POSTN levels, depending on tumor metastatic status, volume of the tumors, subtypes of tumor lesions and specific microenvironment of tumor cell." (PMID 35831854, 2022). "The expression of POSTN in the tumor tissue was higher than that in the adjacent normal tissue." (PMID 35832544, 2022). "Some studies indicated that POSTN-integrin interaction could inhibit the ECM–integrin interaction and trigger both the intracellular signaling and activation of some genes connected with tumor progression." (PMID 35163164, 2022).
tumor (continued). "Additionally, we found a significantly negative correlation between periostin tumor concentration and microvessel density at the invasive front." (PMID 35056404, 2022). "POSTN was expressed in the tumor cells and the interstitial cells of LUAD, and the distribution of POSTN in the interstitial cells was denser than that in the cancer cells, which is consistent to previous studies showing that POSTN is a matricellular protein expressed by stromal cells." (PMID 35832544, 2022). "DDR2 expression in tumor cells did not correlate with POSTN expression." (PMID 35884543, 2022). "Moreover, they showed that POSTN, FN1, VCAN, and pro-collagen-I (PCOL-I, newly synthesized COL-I) colocalize in extracellular strand and ring structures, visible inside the metastases and at the tumor-stroma interface." (PMID 34858485, 2021). "The infiltration of TAMs in tumors was mediated by numerous chemotactic factors produced by tumor cells and TME cells including C-C motif ligand 2 (CCL2), CX3C chemokine ligand 1 (CX3CL1), stromal cell-derived factor-1 (SDF-1), colony-stimulating factor-1 (CSF-1) and periostin (POSTN) etc." (PMID 34108959, 2021). "The cell binding study was repeated using these primary tumor cell lines and showed a binding profile very similar to 786-O, with strong binding to fibronectin, collagen VI, and collagen XII and inefficient binding to or repulsion by periostin, lumican, and tenascin C." (PMID 34884982, 2021). "Moreover, fibronectin and periostin, the major ECM proteins, frequently deposit in the pre-metastatic lungs and increase metastasis by enhancing myeloid cell recruitment and through direct interactions with disseminated tumour cells (DTCs)." (PMID 35006432, 2021). "POSTN, finally, was confirmed as a marker for fibroblasts and was expressed in the primary foreskin fibroblasts and in primary tumors, liver metastases and normal colon tissue but not in CC tumor cell lines." (PMID 32049988, 2020). "This was further supported by the lack of FBLN2 expression in the stromal regions of tumours where the metastatic stromal markers TN-C, POSTN, and GAGs26,47,48 were all expressed, as well as FBLN2′s presence around normal ducts where these metastatic markers were absent." (PMID 30237579, 2018). "Interestingly, the 5-gene classifier contained only genes labeled related to activated stroma (POSTN) and basal-like tumor (AHNAK2, SERPINB5, TMPRSS4), and excluded classical tumor-like genes, which might explain the inferior classification performance." (PMID 29675033, 2018). "Interestingly, POSTN was reported to be increased under hypoxic conditions in non-small cell lung cancer, an effect that promoted tumor cell survival." (PMID 27602954, 2016). "Binding of Periostin to various integrins activates the AKT/PKB and FAK-mediated signalling pathway, which promotes angiogenesis and cell survival, and is also involved in tumourigenesis by enabling enhanced tumour cell survival and proliferative and metastatic ability." (PMID 26543579, 2015). "Periostin (POSTN) was identified by microarray RNA profiling studies as a stromal factor involved in maintaining the normal stem cell niche and demonstrated to be secreted by stromal fibroblasts, but not by infiltrating tumor cells." (PMID 26086719, 2015). "It is noteworthy that POSTN was not expressed in the tumor cells of the samples analyzed." (PMID 21611158, 2011). "Therefore, it is possible that in non-recurrent tumors, in which the POSTN module is repressed, the stroma has fewer interactions with tumor cells, somehow disabling metastasis development." (PMID 21489260, 2011). "However, the regulation mechanisms of periostin in tumour progression have not been elucidated so far." (PMID 20534149, 2010). "It is not clear yet whether periostin upregulation reflects only the stroma re-modeling process per se or whether it is actively induced by the tumour cells themselves." (PMID 20534149, 2010).